CLDN14 (claudin 14)
Description:
Plays a major role in tight junction-specific obliteration of the intercellular space, through calcium-independent cell-adhesion activity.
Synonyms: DFNB29
Tractability: Antibody: UniProt places it where antibodies can reach, with medium confidence; UniProt predicts a signal peptide or a membrane-spanning region; its Gene Ontology location is reachable by antibodies, with medium confidence.
Gene: Protein-coding gene on chromosome 21 (36,460,616 to 36,576,569, reverse strand). Ensembl gene ENSG00000159261.
Subcellular location: Cell junction, tight junction; Cell membrane
Subcellular location (Human Protein Atlas): Vesicles
Pathways (Reactome):
Cell-Cell communication: Tight junction interactions
Gene Ontology:
Molecular function: protein binding; identical protein binding; structural molecule activity
Biological process: calcium-independent cell-cell adhesion; protein-containing complex assembly
Cellular component: endoplasmic reticulum; plasma membrane; bicellular tight junction; membrane
Genetic constraint (gnomAD): Loss-of-function variants: 4 observed, 4.64 expected, observed/expected ratio (o/e) 0.86, 90% interval 0.42 to 1.75. That is too few expected variants to judge how well the gene tolerates losing a copy. Missense variants: 298 observed, 338.66 expected, observed/expected ratio (o/e) 0.88, 90% interval 0.8 to 0.97. Synonymous variants: 136 observed, 158.27 expected, observed/expected ratio (o/e) 0.86, 90% interval 0.75 to 0.99.
Gene-disease validity (ClinGen):
ClinGen rates the evidence that CLDN14 causes each of these diseases.
nonsyndromic genetic hearing loss (autosomal recessive): Definitive.
Homologues: Orthologues: chimpanzee CLDN14 (100% identical), macaque CLDN14 (97% identical), mouse Cldn14 (93% identical), rat Cldn14 (93% identical), guinea pig CLDN14 (92% identical), pig CLDN14 (90% identical), dog CLDN14 (89% identical), rabbit CLDN14 (87% identical), tropical clawed frog cldn14 (59% identical). Paralogues in human: CLDN2 (44% identical), CLDN1 (40% identical), CLDN19 (39% identical), CLDN4 (39% identical), CLDN3 (39% identical), CLDN7 (38% identical), CLDN9 (38% identical), CLDN6 (37% identical), CLDN17 (36% identical), CLDN5 (36% identical), CLDN8 (33% identical), CLDN20 (32% identical), and 10 more.
Diseases named in the same sentence as CLDN14 in open-access papers:
CLDN14 is named in the same sentence as 42 diseases in open-access papers, as found by Europe PMC text mining. Sharing a sentence is not in itself a finding about the gene and the disease. The quoted sentences say what the papers report.
kidney stones (18 papers, 2013 to 2025). "In another study, it was reported that rs199565725 in CLDN14 showed the strongest association with kidney stones." (PMID 39345805, 2024). "In a GWAS study, it was reported that single nucleotide polymorphisms (rs219778, rs219779, rs219780 and rs219781) in the CLDN14 gene were associated with kidney stones, calcium excretion and bone mineral density." (PMID 39345805, 2024). "Various variants of the CLDN14 gene have been linked to hearing loss and the formation of kidney stones." (PMID 38790217, 2024). "Two phenotypes, hearing loss and kidney stones, were reportedly associated with variations in the CLDN14 gene." (PMID 35291565, 2022). "We performed an in silico analysis of CLDN14 variants by employing different databases for nephrolithiasis and hearing loss phenotypes to determine the role of CLDN14 variants on gene regulation and protein structural stability." (PMID 35291565, 2022). "Many synonymous variants in the CLDN14 gene were reportedly linked to kidney stone formation and reduced bone mineral density." (PMID 35291565, 2022). "Based on accumulating evidence, a dysfunction in CLDN14 is highly associated with kidney stone formation." (PMID 33808324, 2021). "Some single-nucleotide polymorphisms (SNPs) of CLDN14 are associated with 24 h urinary Ca2+ excretion and/or kidney stones." (PMID 32164158, 2020). "Some single-nucleotide polymorphisms of CLDN14 are associated with urinary calcium excretion and/or kidney stones." (PMID 32164158, 2020). "A recent genome-wide association study (GWAS) mapped the entire human genome and found SNPs in claudin 14 (CLDN14) that was strongly associated with kidney stone." (PMID 26107257, 2015). "That GWAS in 3,773 kidney stone cases and 42,510 controls from Iceland and the Netherlands reported an association of CLDN14 with nephrolithiasis." (PMID 23991001, 2013). "CLDN14 can restrict paracellular calcium flux and is associated with kidney stone formation." (PMID 41325524, 2025). "Moreover, the findings point to the likelihood that single-nucleotide CLDN14 variants that correlate with high urinary Ca2+ and kidney stones cause a gain-of-function of CLDN14 expression." (PMID 41325524, 2025). "Besides CLDN16 and CLDN19, in 2009, a genome-wide association study on an Icelandic and Dutch population revealed that a CLDN14 variant (rs219780[C]) is associated with kidney stones too." (PMID 31694170, 2019). "The strongest signal associating with kidney stones is a two base pair deletion in intron 1 of CLDN14 rs199565725[delAC] (MAF=23.68%, OR=0.81, P=4.7 × 10−13) correlating with the previously reported sequence variant rs219780[T] (r2=0.82, OR=0.81, P=2.6 × 10−11)." (PMID 26272126, 2015). "To further elucidate the role of PKA and STAT3 in the CaSR-claudin-14 pathway, we treated a rat model of ethylene glycol-induced kidney stones by co-administering the CaSR activator R568 along with the PKA inhibitor or the STAT3 inhibitor." (PMID 39697555, 2024). "Our previous study demonstrated that CaSR and claudin-14 expression was enhanced during the modeling of kidney stones in rats." (PMID 39697555, 2024). "Eventually, a Cldn-14 knockout rat model and a model of kidney stone induction by ethylene glycol were generated using CRISPR-Cas9 technology to further clarify the role of claudin-14 in the CaSR-regulated formation of kidney stones." (PMID 39697555, 2024). "To summarize, targeted inhibition of PKA and STAT3 can attenuate the stimulatory impact of CaSR on claudin-14, thus inhibiting kidney stone formation." (PMID 39697555, 2024). "The first GWAS on nephrolithiasis was reported in 2009, which identified CLDN14 as a significant locus for nephrolithiasis." (PMID 35910217, 2022). "We found two SNPs, rs219779 (C > T) and rs219780 (G > A), through Sanger sequencing of CLDN14 coding exon 3 and UTRs in patients with kidney stones." (PMID 35291565, 2022).
kidney stones (continued). "This study aimed to determine the role of the CLDN14 gene in nephrolithiasis-affected individuals of the local Pakistani population." (PMID 35291565, 2022). "Some genes are the most highlighted ones in recurrent kidney stones, like Vitamin D Receptors (VitD R), Claudin 14 (CLDN14), and Calcium-sensing receptor (CaSR)." (PMID 35546405, 2022). "We aimed to check the association between promoter hypermethylation vitamin D receptor (VDR), calcium-sensing receptor (CaSR), and claudin 14 (CLDN14) genes in recurrent kidney stones." (PMID 35546405, 2022). "We investigated polymorphisms in 200 kidney stone patients and 200 controls by direct sequencing of VDR, CaSR and CLDN14 genes." (PMID 26107257, 2015). "Therefore, this study aimed to elucidate the relationship between the CaSR-claudin-14 pathway and stone formation, and to clarify how CaSR modulates claudin-14 expression, exploring potential intervention points for kidney stones." (PMID 39697555, 2024). "In addition, CLDN14 expression is responsible for decreased urinary Ca2+ reabsorption during elevated serum Ca2+ levels, and dysregulation of CLDN14 contributes to the development of nephrolithiasis." (PMID 33808324, 2021). "Earlier study has reported that CLDN14 expression is strongly upregulated by activation of CaSR and dysregulation of renal CaSR-CLDN14 pathway could contribute significantly to the development of kidney stone." (PMID 26107257, 2015). "We screened the kidney stones associated variants for their association to serum level of biochemical traits and detected association of variants at ALPL with ALP, SLC34A1 with PTH, and creatinine, phosphate and CLDN14 with PTH, magnesium and potassium." (PMID 26272126, 2015). "CLDN14 is of high biomedical importance in this context, as non-coding single nucleotide variants within the CLDN14 gene correlate strongly with both high urinary Ca2+ and kidney stones." (PMID 41325524, 2025). "In this study, CLDN1 expression was found to be increased in patients with a history of recurrent kidney stones and to be highly positively correlated with CLDN4, CLDN7 and CLDN14 and moderately correlated with CLDN2 and CLDN8." (PMID 39345805, 2024). "Our results elucidated the significance of genetic variation at WDR72, DGKH, CLDN14, SLC34A1, and HIBADH in Chinese patients with nephrolithiasis." (PMID 35910217, 2022). "In this study, we investigated the pathogenetic role of CaSR, CLDN14 and VDR genes in kidney stone patients from the Indian population." (PMID 26107257, 2015).
deafness (12 papers, 2007 to 2025). An inherited or acquired condition characterized by the complete loss of the ability to hear from one or both ears. "We show that a deafness-causing missense mutation in human claudin-14 (hCldn14) involves a Cis-1 interface key residue, further validating its biological relevance." (PMID 30271933, 2018). "Initially, CLDN14 was considered the cause of congenital recessive and profound deafness, and more recently of milder forms of hearing loss." (PMID 27838790, 2017). "Expression of claudin-14, which is expressed in TJs of the organ of Corti, and its mutations cause deafness, was examined using whole mount immunostaining, but no changes were observed in Occ−/− mice." (PMID 25063198, 2014). "In fact, mutation of the Claudin-14 gene was reported to cause human hereditary deafness and Claudin-11 null mice exhibit severe deafness associated with low endocochlear potential." (PMID 18154640, 2007). "Moreover, we conducted a comprehensive review of all reported deafness-related CLDN14 mutations and their associated phenotypes." (PMID 38790217, 2024). "In the present study, genetic screening for 68 previously reported deafness causative genes was carried out to identify CLDN14 variants in a large series of Japanese hearing loss patients, and to clarify the prevalence and clinical characteristics of DFNB29 in the Japanese population." (PMID 31527509, 2019). "In addition, we found that a missense mutation in a Cldn14 that causes deafness and contributes stronger to Cis-1 than to X-1 prevents strand formation in cultured cells." (PMID 30271933, 2018). "The mutations in TRIC, a gene encoding human tricellulin, were reported to be responsible for hereditary deafness DFNB49, and knockin mice mimicking human mutation exhibit deafness associated with progressive hair cell degeneration, as observed in Occ−/−, claudin-14 and claudin-9 mutant mice." (PMID 25063198, 2014). "Most notably, claudin-14 has been localized to the junctional complexes of hair cells and supporting cells; mutations in claudin-14 have been shown to cause extensive hair-cell loss and deafness." (PMID 19696885, 2009). "Similarly, claudin 14 mutation was also reported to induce the hair cell degeneration by altering ionic permeability of the paracellular barrier for K+ to further cause human deafness." (PMID 34046408, 2021). "The barrier functions are speculated to be dependent on the combinations of these claudins, and previous reports have shown claudin-9, claudin-11, and claudin-14 to be critical for hearing functions, with mutations in these proteins causing deafness in humans and mice." (PMID 31527509, 2019). "Among these, claudin-14, tricellulin, and angulin-2 are reported to be responsible for human deafness DFNB29, DFNB49, and DFNB42, respectively." (PMID 31527509, 2019). "One of these, CLDN14 (DFNB29) is a known deafness gene expressed in the sensory epithelium of the organ of Corti of the inner ear." (PMID 27838790, 2017). "Neither pathogenic loss-of-function CLDN14 variants in patients nor Cldn14 deficiency in mice lead to an altered Ca2+ balance, but instead result in nonsyndromic deafness." (PMID 41325524, 2025). "The Cldn11 gene, which encodes Claudin-11, has not, thus far, been identified as a deafness gene while mutations in the genes encoding Claudin-14 (DFNB29) and Claudin-9 cause autosomal recessive deafness in humans and mice." (PMID 28848383, 2017). "Knockout mice of claudin-14 were demonstrated to develop deafness." (PMID 25063198, 2014). "Although the CLDN14 gene is relatively small, it consists of a single coding exon, has a coding region of 720 nucleotides, and is associated with a limited number of mutations linked to hearing loss; another gene, GJB2, with a similar structure (one single coding exon) is also involved in deafness." (PMID 38790217, 2024).
hearing loss (12 papers, 2014 to 2024). "After considering genes responsible for hearing loss, we narrowed down the list of candidate variants to a lone known variant located within the CLDN14 gene." (PMID 38790217, 2024). "Numerous mutations in CLDN14 were reportedly associated with hearing loss, and all exhibited higher genetic scores, according to the American College of Medical Genetics and Genomics guidelines." (PMID 35291565, 2022). "The CLDN14 variants are a relatively common cause of recessive hearing loss, which is responsible for 2.25% of HL patients in a Pakistani study cohort, whereas no pathogenic variants were reported from east Asian populations." (PMID 31527509, 2019). "In these, one type of claudin gene, CLDN14, was reported to be responsible for human hereditary hearing loss, DFNB29." (PMID 31527509, 2019). "CLDN14 p.(Ala163Val) appears to be of Irish origin and causes a precipitous, prelingual recessive sensorineural hearing loss." (PMID 27838790, 2017). "A population-based study of hearing loss in the NL population has clarified the role of CLDN14 p.(Ala163Val), a VUS previously identified in the USA, Iceland and Sweden." (PMID 27838790, 2017). "The role of CLDN14 in nonsyndromic hearing loss was first described in two large consanguineous families from Pakistan with recessive profound congenital deafness." (PMID 27838790, 2017). "Among the 163 upregulated genes, we did not observe a clear enrichment of Gene Ontology processes but did obtain significant enrichment of genes associated with hearing loss, including the upregulation of Otof, Tectb, Cldn11, Sall1, Cldn14, Chrna10, Esprn, and Fgfr3." (PMID 38564333, 2024). "Several CLDN14 variants have been associated with hearing loss and renal stone formation." (PMID 35291565, 2022). "Furthermore, our study suggested that hearing loss was associated with genetically strong monogenic mutations in CLDN14 causing protein instability, whereas stone-associated variations of CLDN14 affected gene regulation." (PMID 35291565, 2022). "Recessive CLDN14 alleles manifest as nonsyndromic sensorineural hearing loss with considerable phenotypic variability and may present as congenital or prelingual, and mild, moderate–severe or profound." (PMID 27838790, 2017). "In the present study, we conducted genetic analyses of the TJP2 and CLDN14 genes in 87 unrelated patients with ADNSHL and 48 unrelated patients with either ARNSHL or potentially sporadic hearing loss." (PMID 24752540, 2014). "In silico analysis revealed that mutations associated with hearing loss were not correlated with renal stone formation but affected claudin-14 protein stability." (PMID 35291565, 2022). "Our findings suggest that whereas two variations in the TJP2 gene are casually linked to hearing loss, variations in the CLDN14 gene do not make a major contribution to the etiology of hearing loss in Korean patients." (PMID 24752540, 2014).
Hypercalciuria (5 papers, 2013 to 2025). "In mice lacking the parathyroid hormone 1 receptor in the distal tubule, hypercalciuria develops alongside increased Cldn14 expression and this phenotype is rescued upon Cldn14 deletion." (PMID 41325524, 2025). "This activates a signaling cascade where the expression of Claudin-14 disrupts Mg reabsorption, contributing to hypermagnesuria and hypercalciuria, which can further exacerbate existing subclinical hypomagnesemia." (PMID 39885554, 2025). "The overexpression of claudin-14 in the thick ascending limb of Henle’s loop of the kidney generates a renal phenotype characteristic with hypomagnesemia and hypercalciuria." (PMID 26107257, 2015).
colorectal cancer (4 papers, 2022 to 2024). A primary or metastatic malignant neoplasm that affects the colon or rectum. "CLDN14, an upregulated prognostic gene, influence colorectal cancer progression through controlling the PI3K/AKT/mTOR pathway." (PMID 37799140, 2023). "Our findings revealed that the mRNA expression levels of CLDN1, CLDN2, CLDN12, and CLDN14 were upregulated in colorectal cancer tissues relative to normal tissues in the Oncomine database, whereas CLDN3, CLDN5, CLDN7, CLDN8, CLDN11, CLDN15, and CLDN23 were downregulated, as previously reported." (PMID 35281827, 2022). "In addition, three genes were shown to be related with advanced colorectal cancer: CLDN11 (p = 0.007), and CLDN14 (p = 0.03) and CLDN23 (p = 0.021)." (PMID 35281827, 2022).
gastric cancer (4 papers, 2013 to 2023). A primary or metastatic malignant neoplasm involving the stomach. "CLDN14 was also found up-regulated in gastric cancer tissues and was related to E-cadherin expression and lymph node metastasis." (PMID 36098705, 2022). "The membrane staining of claudin-14 was strong in gastric cancer tissues and weak in adjacent tissues." (PMID 24325792, 2013). "We conclude that claudin-14 expression is significantly higher in gastric cancer samples than in histologically normal gastric tissue." (PMID 24325792, 2013). "Our study reveals that the expression of E-cadherin, claudin-10, and claudin-17 were down-regulated in gastric cancer tissue while the expression of claudin-14 was up-regulated and correlation between claudins and E-cadherin expression with lymphatic metastasis were observed." (PMID 24325792, 2013). "Claudin-14 was expressed in 58.0% (29/50) of gastric cancer tissues." (PMID 24325792, 2013). "The present work infers that the expression altered of claudin-10, claudin-14, claudin-17 and E-cadherin between human gastric cancers and adjacent non-neoplastic tissues correlate with lymph node metastasis." (PMID 24325792, 2013).
breast carcinoma (3 papers, 2022 to 2024). "Claudin-14 (CLDN14) has been shown to be downregulated in breast carcinoma." (PMID 38540693, 2024). "For example, CLDN11 and CLDN14 are correlated with prognostic values in human breast carcinoma." (PMID 37799140, 2023).